NANOG (Nanog homeobox)
Diseases named in the same sentence as NANOG in open-access papers (continued):
Sharing a sentence is not in itself a finding about the gene and the disease.
cancer (continued). "Finally, the overexpression of target gene NANOG is a significant indicator of castration-resistant prostate, contributing to cell proliferation, cancer cell regeneration, induction of the shortened cell cycle, severe invasiveness, and cancer metastasis." (PMID 35164166, 2022). "Consistently, IL-6/STAT3 signaling in cancerous EMT also results in the acquisition of cancer stemness in cancer cells; the self-renewal and population expansion of CSCs requires STAT3 in cooperation with stem-cell-associated transcription factors, such as NANOG." (PMID 36010693, 2022). "One mechanism that could explain this lower HNSCC incidence is the downregulation of cancer stemness and epithelial–mesenchymal transition-related genes, such as OCT4, SOX2 and NANOG, observed after metformin treatment, which could inhibit progression in cancer-initiating cells." (PMID 35327549, 2022). "However, despite the relevance of NANOG expression in ICB therapy–refractory cancer, the precise mechanism by which NANOG could trigger resistance to ICB therapy, especially through HDAC1-mediated epigenetic reprogramming, is not well understood." (PMID 35104240, 2022). "Also, NANOG acts as a cancer stemness marker and promotes cancer tumorigenesis and stemness." (PMID 33439550, 2021). "Therefore, we investigated the role of human NANOG in CXCR4-mediated cancer cell migration." (PMID 34638956, 2021). "Consequently, the silencing of NANOG reduced FAO, resulting in the loss of cancer stemness." (PMID 33804114, 2021). "However, the employment of specific inhibitors of Glut1 transporters, such as WZB117, has been demonstrated to affect tumor insurgence through the downregulation of stemness-associated genes, such as SOX2, NANOG and BMI1 in different cancers including pancreatic, ovarian and glioblastoma cancer." (PMID 34249759, 2021). "Thus, apart from its well-established role as a pluripotency transcriptional factor, our findings together with the published data suggest that NANOG may be a marker of therapy resistance and cancer progression." (PMID 34203746, 2021). "In addition, the downregulation of SPN also induces an increase in the stemness properties of the cells, such as the expression of some cancer stem cell markers (NANOG, OCT4, SOX2, and KLF4) and enrichment in CD44+/CD24- cells, cancer-initiating cells in breast tumors with stem cell properties." (PMID 34066428, 2021). "Thus, strategies impeding the NANOG-signaling pathway may not only conquer the problem of therapeutic resistance but also that of the stem-like state in cancer." (PMID 31992715, 2020). "Therefore, our data provide evidence that the inhibition of HSP90A may be a promising strategy that will help combat NANOG+ immune-refractory tumors, particularly in regard to immune-based cancer therapy." (PMID 31992715, 2020). "However, due to the role of TEs in development and their interactions with pluripotency factors such as OCT4 and NANOG, along with the known activation of such factors in many cancers we believe this hypothesis warrants further investigation." (PMID 32432029, 2020). "Specifically, NANOG has been shown to be upregulated in different types of cancers including OSCC, and its overexpression has been correlated with poor differentiation status, poor prognosis, and chemoresistance, suggesting that NANOG may promote aggressive tumor phenotypes." (PMID 31484317, 2019). "This study demonstrated that tumor tissue cells harvested from PCa patients exhibited high NANOG expression and low ICAM1 expression, and PCa patients expressing low levels of ICAM1 had a higher risk of recurrence than those expressing high levels of ICAM1 after surgical cancer resection." (PMID 31619256, 2019).
cancer (continued). "Our finding might seem contradictory to the stemness role these pluripotent transcription factors play; however, it is worth to emphasize that the mechanistic functions of SOX2, OCT4, and NANOG in cancer cells are a little different in each stage of tumor progress." (PMID 29849920, 2018). "In addition to constitutive expression of NANOG in a small subset of cancer cells, NANOG may also be induced by tumor microenvironments such as inflammatory cytokines and hypoxia." (PMID 27867534, 2016). "Accumulated evidence from various cancer types strongly support the hypothesis that hypoxia sustains the self-renewal characteristics of a portion of cancer cells in hypoxic niches mainly due to the upregulation of Oct4, NANOG, SOX2, Klf4, and c-myc." (PMID 26042045, 2015). "Moreover, several studies have shown that NANOG regulates different functions of cancer development, such as tumor cell proliferation, drug-resistence and cancer cell communication with the surrounding stroma, leading to cell motility, epithelial-mesenchymal transition and immune evasion." (PMID 24586330, 2014). "Our observations of modern polymorphisms in NANOG and NANOGP8 underscore the unreliability of variants between reference sequences for accurate experimental distinction of NANOGP8 from NANOG RT-PCR products, particularly in studies of gene expression in cancer cells." (PMID 23173096, 2012). "In addition, the expression of OCT4 and NANOG was studied in all cancer cell lines." (PMID 21785609, 2011). "We next performed Western blot analysis to examine the effects of meranzin hydrate on two cancer stemness markers (ALDH1A1 and NANOG) in GBM cells." (PMID 41473403, 2026). "In this regard, our previous studies demonstrated that CTL-mediated immune selection enriches immune-refractory cancer cells with CSC-like properties and resistance to CTL-mediated apoptosis, driven by E2F1 through FGFR signaling or NANOG induction." (PMID 41339438, 2025). "We observed that manipulation of DUSP9 expression led to corresponding changes in the expression of core cancer stemness genes, including SOX2, NANOG and OCT4." (PMID 41383134, 2025). "ID2 induces the expression of nanog homeobox (NANOG) and sry‐box transcription factor 2 (SOX2), which are cancer stem cell markers, through the PI3K/AKT pathway, and contributes to cell proliferation and cancer stem cell maintenance." (PMID 40448344, 2025). "Another study also proved that 5FU resistant cancer cells show an upregulation of CSC marker proteins like CD44, OCT4 and NANOG." (PMID 40045186, 2025). "The study was conducted to evaluate the immunohistochemical expression of cancer stem cell markers (CSM) OCT-4 and NANOG in OSMF (OSMF) patients, OSCC transformed from OSMF (OSCC+OSMF) patients, and OSCC not transformed from OSMF (OSCC-OSMF) patients." (PMID 41376750, 2025). "A novel LIFR inhibitor, EC359, resulted in the induction of apoptosis and reduced the levels of cancer stem cell markers SOX2, OCT4, and NANOG in EC." (PMID 40804837, 2025). "Ectopic NANOG expression occurs frequently in human CRC tumors and exhibits pronounced enrichment within cancer stem cells (CSCs)." (PMID 41214698, 2025). "Consistently, TFAP2A enhanced the protein levels of cancer stem cell markers and stemness-related genes, including CD44, CD133, NANOG, OCT-4A and SOX2." (PMID 40727938, 2025). "Consistent with the previously noted impact of miRNA-21 on stemness and survival in other cancers, we observed that silencing miRNA-21 led to a significant downregulation of key stemness markers OCT4, SOX9, and NANOG." (PMID 39851519, 2025).
cancer (continued). "NANOG is a key regulator of stem cell properties, and CD44 is involved in cell adhesion, movement, and signaling, both playing roles in cancer stem cells (CSCs) in PDAC." (PMID 40429900, 2025). "NANOG, SOX2, and OCT4 are highly critical stemness genes that promote cancer stem cell (CSCs)-related characteristics including the self-renewal of CSCs." (PMID 40806148, 2025). "In our previous investigations, we have successfully isolated and characterized CD44+ cells in which the expression of embryonic/cancer stem cell markers OCT4, SOX2, and NANOG was significantly higher than in the CD44− cell populations." (PMID 39941011, 2025). "Researchers aim to block the molecular pathways that facilitate cancer cell survival and proliferation by developing inhibitors or modulators of STAT and NANOG activity." (PMID 40729003, 2025). "Hypoxia and HIF1 are generally known to be important in cancer stem cell development, inducing, for example, the expression of OCT4, SOX2, NANOG and Krüppel-like factor 4 (KLF4) as stem cell markers." (PMID 38773108, 2024). "Organoid formation and expression of cancer stem cell markers such as ABCG2, NANOG, and CD44 were altered by conditioned media from treated MAFs." (PMID 38791392, 2024). "It activates the expression of NANOG and FGFBP1 in TNBC, which are required for the maintenance of the cancer stem cell (CSC) population." (PMID 38468288, 2024). "This study provides new molecular insights into the role of NANOG as a key determinant of pluripotency in TGCTs through the regulation of MIR9-2-5p, a novel epigenetic modulator of cancer stemness." (PMID 38693576, 2024). "Shikonin reduced the expression of diverse cancer stem cell markers like ALDH3A1, CD133, EZH2, NANOG, and SOX2." (PMID 38612718, 2024). "Treatment with most of the extracts induced a significant decrease in the relative expression of the cancer stem cell (CSC)-related genes CD24, CD133, NANOG and OCT-4." (PMID 39683626, 2024). "These compounds were also shown to reduce stemness markers, namely, CD133, NANOG, MgSOD, and SOX2, in various in vitro and in vivo cancer models, with implication of c-Met signalling inhibition in the mechanism of action." (PMID 38612718, 2024). "Stemness, known as the self-renewal capacity of cancer stem cells, is regulated by many signaling pathways, including TGF-β, Hedgehog, Wnt, Notch, and FGF, and transcription factors, including NANOG, OCT4, SOX2, KLF4, and c-MYC." (PMID 39516821, 2024). "According to RNA-seq data in MCF-7 spheroids, stemness-related genes, such as SOX2 and NANOG, which have been reported to regulate CSC properties in a wide range of cancers, were significantly decreased in siNSDHL compared to siCtrl." (PMID 39516821, 2024). "CBLL1 silencing was confirmed at the mRNA level, and mRNA downregulation of other known stem cell markers including LGR5, NANOG and c-MYC was also detected in sh-CBLL1 HT29 cancer stem cell tumourspheres compared to sh-control tumourspheres." (PMID 38339195, 2024). "The pluripotent transcription factors KLF4, NANOG, OCT4, and SOX2 are essential for maintaining cell stemness in cancer." (PMID 38233377, 2024). "In this study, we examined the expression of the pluripotency genes (NANOG, SOX2, and POU5F1) and the ALDH1A1 gene in ER+ BC tumors across three large cancer datasets." (PMID 38400679, 2024). "Instead, a high expression of NANOG and Zeb-1 and an expression of CDH-1, similar to that detected in ground control cells characterized BR95 cancer cells, well identify their mesenchymal character." (PMID 39451527, 2024). "This study was done to evaluate the cancer stem cells in OSCC and OED using immunoexpression of NANOG." (PMID 38558704, 2024). "Thus, NANOG could be a potential target for cancer therapy, in addition to prevent carcinogenesis." (PMID 38846985, 2024).
cancer (continued). "Key regulators of normal and cancer stem cells including the transcriptional factors OCT4, NANOG, and SOX2 were found significantly decreased in KK-LC-1 knockout cells at both mRNA and protein levels." (PMID 37147285, 2023). "This process also requires the expression of cancer stemness TFs OCT-4, NANOG, and SOX2, emphasizing the role of TFs in cancer cell-myCAF crosstalk, as also demonstrated in MBA-MB-231 breast cancer and HepG2 hepatocellular carcinoma cells." (PMID 38124183, 2023). "Stem-cell-related factors, such as SOX2, KLF4, NANOG, OCT4, ALDH1, and ALDH2, have been reported to be vital for maintaining cell self-renewal traits in many types of cancer." (PMID 36674577, 2023). "It is important for promoting the CSC phenotype, prompting de-differentiation of cancer cells to CSCs, as well as inducing the expression of pluripotent stem cell markers, OCT4, NANOG, SOX2, KLF4, c-MYC." (PMID 37614497, 2023). "Both pluripotency (NANOG and MYC) and mitochondrial activities are positively correlated with stemness scores in single cancer cells." (PMID 37463926, 2023). "It was also demonstrated that the formation of spheroid cells and expression of NANOG were suppressed, thus indicating the prospective governing role of miR-520b in OSCC cancer stemness." (PMID 38170015, 2023). "NANOG, SOX2, and OCT4 are well-known transcription factors essential for maintaining self-renewal and pluripotency in both normal and cancer stem cells, including BCSC and OCSC." (PMID 37445860, 2023). "The doxorubicin treatment displayed a favorable gene signature among surviving cancer cells with low proliferation (MKI67) and pluripotency features (NANOG, POU5F1), in comparison to 5-fluorouracil showing low proliferation but increased pluripotency." (PMID 38124067, 2023). "The expression of EPCAM increases the expression of stemness markers (NANOG, SOX2, and OCT4) in cancer cells, and EPCAM has been described as a marker of cancer stem cells in colorectal, prostate, pancreatic, and breast cancers." (PMID 36674577, 2023). "Previous studies have established NANOG and OCT4 as distinguishing factors for CSCs, and the expression of these genes has been found to have detrimental effects on cancer patients." (PMID 37372456, 2023). "In the present study, we found that the STAT3 signaling pathway played an important role in mediating the function of IL20RB in promoting cancer stemness and chemoresistance, and IL20RB-STAT3 signaling promoted the expression of NANOG, SOX2 and POU5F1." (PMID 38098005, 2023). "Our previous research revealed the significant expression of embryonic stemness genes, NANOG and OCT4, in CSCs, suggesting their role in enhancing cancer-specific stemness and drug resistance." (PMID 37372456, 2023). "Abnormal expression of NANOG, a differentiated HOX domain protein, has been reported in several human cancers including breast cancer, lung cancer, adenocarcinoma, and gastric cancer." (PMID 37614497, 2023). "In accordance, ATF1 is positively correlated with both pluripotent (33/33, 23/33 of cancer types for MYC and NANOG, respectively) and mitochondrial regulators (33/33 of cancer types for both TFAM and NRF1) in TCGA cohorts." (PMID 37463926, 2023). "MYC is one of the well-characterized transcription factors, including OCT4, SOX2, NANOG, KLF4, in cancer stem cell establishment, maintenance, and functions." (PMID 36941257, 2023). "FOXD3 as an epigenetic regulator mediates the transcriptional repression of multiple cancer genes including SLC25A26 and NANOG." (PMID 36966276, 2023). "By targeting NANOG and OCT4, we can minimize disturbances to the viability and function of normal adult cells, focusing on the therapeutic impact on cancer cells that overexpress these genes." (PMID 37372456, 2023). "Meanwhile, other cancer stemness-related markers, such as OCT4, NANOG and C-MYC were also slightly induced after SRC activation." (PMID 36633714, 2023).
cancer (continued). "The third cluster of the built PPI network is well represented by transcriptional factors e.g., such as SOX2, NANOG and POU5F1/OCT4, which are considered cancer stem cell (CSC) markers." (PMID 37445716, 2023). "Pluripotent transcription factors, including NANOG, SOX2, and OCT3/4, contribute to the establishment of stem cell-like properties in cancer cells, similar to embryonic stem cells." (PMID 36564568, 2022). "Among the EOC tissues examined, CXCR4 expression correlated strongly with expression of proteins related to the epithelial-mesenchymal transition (EMT) and cancer stem cell (CSC), including vimentin, N-cadherin, E-cadherin, CD44, CD133, and NANOG." (PMID 35681259, 2022). "Using real-time reverse transcription-PCR (RT-qPCR), we discovered that several canonical stem cell makers, including NANOG, CD133, and OCT4, were up-regulated in the soft-fibrin-gel-selected cancer cells, which confirmed their cancer stem cell identity." (PMID 36127710, 2022). "Several markers have been identified in cancer stem cells like CD133, CD 166, CD44, CD40, and NANOG." (PMID 35186145, 2022). "HIF-1 regulates expression of cancer stem cell markers like KLF4, MYC, OCT4, SOX2, and NANOG, and thus help cancer cells to survive through hypoxic crisis." (PMID 36253762, 2022). "Cancer cell stemness is regulated by a strong transcriptional circuit constituted by OCT4, SOX2, and NANOG." (PMID 36568166, 2022). "Further, several studies have shown that hypoxia and HIF induce cancer cells to express stem cells-like phenotype by upregulating the expression of OCT4, SOX2, and NANOG 127,128." (PMID 35812177, 2022). "Consistently with previous studies, our results indicate that SALL4 in concert with other stemness markers like OCT4, NANOG, and SOX2 can drive reprogramming of cancer cells toward a CSC-like phenotype mediated by the TWIST1 expression." (PMID 36474162, 2022). "Knockdown of NANOG or HDAC1 with a siRNA robustly dampened expression of the effectors of NANOG signaling, such as CXCL10 and MCL1, across all tested cancer cells." (PMID 35104240, 2022). "In this study, we present for the first time positive correlations of SHMT2 expression with the expression of cancer stem cell markers, such as OCT4, SOX2, and NANOG, and the aggressiveness of HNC." (PMID 36077112, 2022). "Cancer stemness markers, OCT4, SOX2, and NANOG, were found to be significantly decreased upon miR‐181a inhibition." (PMID 35029026, 2022). "To further investigate the relationship between cancer stem cell-like properties and CMTM2, we detected the expression of stem cell markers SOX2, NANOG, and CD44 in SGC7901 cells using qRT-PCR and western blotting." (PMID 35873650, 2022). "Expressions of cancer stem cell-related genes ABCG2, NANOG, ALDH1, OCT4, and SOX2 were significantly down-regulated in si-RSU1P2-1 and si-RSU1P2-2 groups compared to si-NC group (p < 0.05)." (PMID 35156514, 2022). "Our results showed that SJZ treatment inhibited the spheroid and colony-forming capacities of SGC7901 cells, accompanied by downregulation of cancer stem cell markers such as SOX2, NANOG, and CD44." (PMID 35873650, 2022). "Cancer stem cells have a specific gene signature, and the principal markers are SOX2, OCT4, and NANOG." (PMID 35965510, 2022). "CXCR4/CXCL12 signaling also activates the Hh pathway in other cancer types, thus increasing tumor size, cell motility, angiogenesis, EMT, cell invasion, and NANOG expression." (PMID 36118530, 2022). "Several studies have demonstrated that acute hypoxia selects for cancer cells with stem cell characteristics, enhancing stem-like cell marker expression, such as OCT4, SOX2, NANOG and MYC, through upregulation of the HIF-1α pathway." (PMID 36224457, 2022). "It has been highlighted that an enhanced population of cancer stem cells (CSCs) contributes to chemoresistance and recurrence, and that ALKBH5 promoted CSC property through increasing FOXM1 and NANOG." (PMID 35628623, 2022).